BTLA (B and T lymphocyte associated)
Diseases named in the same sentence as BTLA in open-access papers (continued):
Sharing a sentence is not in itself a finding about the gene and the disease.
tumor (continued). "Whilst blockade of the PD-L1 signal with an anti-PD-1 antibody clearly sensitized TRAMP-C2 tumours to cytotoxic T lymphocyte (CTL) killing in the current study, results will be presented to show whether blockade of BTLA can synergise with anti-PD-1 at reversing tumour-specific T cell inhibition." (PMID 30400822, 2018). "The proportions of tumor cells in comparison to major stromal cell subsets (CD45+ immune cells, fibroblasts, endothelial cells) were not significantly changed, although, as expected, there was a tendency of reduced tumor cell abundance in anti-BTLA antibody treated tumors." (PMID 29518903, 2018). "Similar to LAG3 blockade, targeting TIM3 and/or BTLA may augment the efficacy of OX40 therapy by supporting the expansion, survival, and cytotoxic effector function of lymphocytes, particularly within the microenvironment of the tumor." (PMID 25763356, 2015). "Notably, BTLA mRNA and protein expression levels do not always align, and spatial distribution within the tumor—such as enrichment at the invasive margin—may provide greater insight than bulk expression alone." (PMID 41471273, 2025). "However, FOXP3 + cells, CD56 + NK-cells, or Cbl-b + cells did not express BTLA in tumor tissue." (PMID 38233898, 2024). "It was found that the risk score had negative correlation with the BTLA, CD27, CD40, CD80, and TNFRSF14 expression, which had significant differences in different risk groups, indicating that tumor immunosuppression might lead to an increased risk score of patients." (PMID 34899848, 2021). "Unlike PD-1 or CTLA-4, BTLA interacts bidirectionally with its ligand HVEM, forming a complex signaling network that shapes immune homeostasis within the tumor microenvironment." (PMID 41471273, 2025). "The six critical genes, including CCR7, FCGR2B, BTLA, CD6, CD3D and CD3E, play important roles in favoring tumor progression and promoting negative immune-regulatory effects." (PMID 36291815, 2022). "In the current study, we observed marked upregulation of BTLA expression on circulating CD4+ but not CD8+ T cells, which is in consistent with our previous studies on BTLA in tumor-infiltrating T cells in HCC patients." (PMID 30116751, 2018). "Such distinct changes of BTLA and HVEM expressions in tumor patients were attributed to the absence of their positive correlation between CD4+ and CD8+ T cells, which can be observed in healthy donors." (PMID 30116751, 2018). "Different modes of immune evasion were seen across 12 tumours with up-regulation or consistent expression of CD47, unlike other immune evasion genes such as PDL1, FUT4, CTLA4 and BTLA which were downregulated in a few samples." (PMID 28886030, 2017). "As BTLA engages HVEM in its first cysteine-rich domain (CRD1) and mutation at the 61 tyrosine to alanine (Y61A) of the HVEM CRD1 domain disrupts the binding to BTLA, we hypothesized that Y61A HVEM could not play a regulatory role in the tumor cell." (PMID 36552785, 2022). "Importantly, BTLA blockade synergizes with PD-1 and TIM-3 blockade in enhancing proliferation and cytokine production by tumor-specific T cells in vitro indicating a non-redundant role for BTLA." (PMID 26347741, 2015). "Further immune profiling of reovirus-treated TRAMP-C2 tumors revealed the upregulation of BTLA, which rather than acting as an inhibitory receptor, appeared to have a critical role in HVEM-BTLA co-signaling in trans, promoting the optimal generation of a potent anti-tumor memory response." (PMID 33665363, 2021).
cancer (145 papers, 2013 to 2026). A tumor composed of atypical neoplastic, often pleomorphic cells that invade other tissues. "The immunoglobulin-associated receptor family (TIGIT, CTLA4, CD274, and BTLA) have inhibitory effects on T cell function and have been used as a part of immunomodulatory strategy for treating cancers." (PMID 40173324, 2025). "Accumulating transcriptomic and immunohistochemical evidence indicates that BTLA is variably expressed across a broad range of human cancers, often in patterns associated with immune suppression or poor prognosis." (PMID 41471273, 2025). "Several previous studies have linked SNPs within the BTLA gene to the risk of cancer development and progression." (PMID 38233898, 2024). "Abnormal BTLA expression has been observed in various cancers, and has been linked to unfavorable disease outcomes." (PMID 38233898, 2024). "Our previous studies on BTLA SNPs in cancer showed an association of rs1982809, rs2705511, and rs9288953 with chronic lymphocytic leukemia (CLL) risk." (PMID 36741370, 2022). "Ultimately, the memory or mature T lymphocytes end up with exhaustion, which modulate cancer eradication and is implicated by cellular surface markers, including programmed death receptor 1 (PD-1) and B and T lymphocyte attenuator (BTLA)." (PMID 34016791, 2021). "Growing evidence suggested that B‐ and T‐lymphocyte attenuator (BTLA) polymorphisms raised the susceptibility to a wide range of cancers." (PMID 32060969, 2020). "A total of 721 ESCC patients and 1208 matched non‐cancer controls were included in this research, and four tagging BTLA polymorphisms (rs2171513 G > A, rs3112270 A > G, rs1982809 G > A, and rs16859629 T > C) were selected and genotyped using SNPscanTM Assays." (PMID 32060969, 2020). "Some studies have kept a watchful eye on the correlation of BTLA variants with the development of cancer." (PMID 31774112, 2019). "In the present study, we first studied the relationship between BTLA rs1982809 locus and cancer risk in Asians." (PMID 31774112, 2019). "BTLA has been linked to a defective anti-tumor immunological response in various cancers." (PMID 39343796, 2024). "As immune checkpoint therapy, especially targeting BTLA, is becoming widely available to cancer patients, it is critical to understand the underlying function and mechanism of these immune checkpoints, thus benefiting patients with advanced cancer." (PMID 36552785, 2022). "BTLA molecule plays a significant role in sustaining immunological self-tolerance and preventing autoimmunity, but its high level of expression can reduce the body’s immunity and cause people to develop various diseases, even cancers." (PMID 35945755, 2022). "Studies have reported that B- and T-lymphocyte attenuator (BTLA) polymorphisms may be associated with the risk to different cancers." (PMID 33564688, 2021). "More studies should be conducted to evaluate whether BTLA polymorphisms may influence the susceptibility of cancer in the future." (PMID 31774112, 2019). "More studies with multiple environment factors should be carried out to evaluate whether BTLA variants may influence the susceptibility of cancer in the future." (PMID 31774112, 2019). "In the future, more case–control studies should be conducted to evaluate whether BTLA rs1982809 G>A polymorphism might inhibit the function of B and T cells and influence the susceptibility of cancer." (PMID 31774112, 2019). "In view of the vital role in cancer development and progress, we supposed that BTLA SNPs might be correlated with EGJA susceptibility." (PMID 31774112, 2019). "We first expolre the association of BTLA haplotypes with cancer risk in Asians." (PMID 31774112, 2019). "Since BTLA is highly expressed on B cells and global BTLA deletion was associated with enhanced auto-immune reactions in a number of studies, caution is warranted when envisioning anti-BTLA antibodies for the treatment of cancer in humans." (PMID 29518903, 2018).
cancer (continued). "Interestingly, the present study first explored that BTLA rs16859629 SNP could promote the susceptibility to cancer." (PMID 33564688, 2021). "Therefore, a BTLAhigh state linked to an active anti-cancer immune response and BTLA may play a positive role in the cancer-immunity cycle." (PMID 33718105, 2020). "Hence, BTLAc.590*A allele was associated with decreased inhibitory activity of BTLA in Jurkat cells it may potentially constitute cancer risk factor." (PMID 33519815, 2020). "B- and T-lymphocyte attenuator (BTLA) has been shown to suppress NK cell function when agonized, and potentially drive cancer suppression upon BTLA blockade." (PMID 41139700, 2026). "In the context of cancer, sustained BTLA signaling contributes to the suppression of effector immunity, supports regulatory and tolerogenic immune phenotypes, and facilitates immune evasion." (PMID 41471273, 2025). "Quantitative Interactomics was used to examine the rationale for concomitant PD-1 and BTLA co-inhibitor blockade in cancer immunotherapy." (PMID 41440959, 2025). "The literature data indicate BTLA upregulation in various cancers, including gallbladder cancer, melanoma, lung cancer, DLBCL, RCC, etc., which is often associated with impaired antitumor T cell responses." (PMID 41301417, 2025). "The growing understanding of BTLA’s biology offers promising avenues for the development of novel cancer immunotherapies." (PMID 41471273, 2025). "These interactions expand the immunoregulatory scope of BTLA far beyond the T cell compartment, influencing both adaptive and innate immune responses in cancer." (PMID 41471273, 2025). "In this section, we examine the relevance of BTLA within the TME by first reviewing its expression across different cancer types." (PMID 41471273, 2025). "Part of these research efforts has focused on circulating BTLA, which has revealed to be a promising blood-based predictive biomarker of immunotherapy response in various cancers." (PMID 41440959, 2025). "In the context of cancer, BTLA promotes immunosuppression, which can weaken the antitumor immune response." (PMID 40574024, 2025). "This precision-driven paradigm holds promise for transforming BTLA from a niche checkpoint into a clinically impactful target in cancer immunotherapy." (PMID 41471273, 2025). "BTLA’s role in immune regulation has made it a promising target for cancer immunotherapy, where blocking its inhibitory effects can restore T cell activity and enhance antitumor responses." (PMID 41440959, 2025). "Circulating BTLA has been identified as a blood-based predictive biomarker for immune therapy responses in various cancers." (PMID 40421217, 2025). "Understanding BTLA’s role in cancer has led to the exploration of therapeutic strategies targeting this pathway." (PMID 38233898, 2024). "A recent review by Andrzejczak and Karabon gives a comprehensive overview of the current understanding of BTLA biology in cancer." (PMID 38928307, 2024). "Recently, BTLA-HVEM interactions have been utilized as a potential target for checkpoint blockades in cancer therapy." (PMID 39343796, 2024). "In this review, our aim is to summarize the current state of knowledge concerning the biology of BTLA, its role in cancer immunosurveillance, and its potential as a prognostic factor in various cancers." (PMID 38233898, 2024). "Nevertheless, despite numerous publications underscoring the significance of dysregulated BTLA expression in cancer, there remains a dearth of knowledge regarding the regulation of BTLA protein expression at the translational and post-translational levels." (PMID 38233898, 2024). "This sets PRCC apart from many other cancers, such as lung, bladder, colon, rectal, and thyroid carcinomas and adenocarcinomas, where BTLA tends to be downregulated and expressed at lower levels in cancer cells compared to their healthy counterparts." (PMID 39796121, 2024).
cancer (continued). "Upregulated expression of BTLA on CD8+ and CD4+ T cells in the TME was associated with unfavorable prognoses for patients with various types of cancer." (PMID 38835768, 2024). "Herpesvirus entry mediator (HVEM) and its ligand B- and T-lymphocyte attenuator (BTLA) have been proposed as promising future targets for cancer immunotherapy." (PMID 38785930, 2024). "In particular, the BTLA-HVEM complex has gained significant scientific interest as a crucial regulator in cancer immune contexts, as recently reviewed." (PMID 39684559, 2024). "This review aims to provide an in-depth understanding of BTLA’s biology, its role in various cancers, and its potential as a prognostic factor." (PMID 38233898, 2024). "The heightened BTLA expression on TILs leads to T-cell exhaustion, reducing their capacity to eliminate cancer cells effectively." (PMID 38233898, 2024). "For cancer associated LR interactions from the immune-to-epithelial, the HGSOC patients had higher ITGA4_MDK and BTLA (to VTCN1 and TNFRSF14)." (PMID 38328306, 2023). "As a potential therapeutic target for cancer immunotherapy, BTLA is similar to PD-1 and CTLA-4, but possesses different functions." (PMID 36765782, 2023). "Icatolimab (TAB004/JS004), as the first BTLA monoclonal antibody, is currently being tested in different clinical trials for cancer treatment (such as studies NCT04278859, NCT04137900, and NCT04477772)." (PMID 36765782, 2023). "In conclusion, compelling evidences indicate that BTLA/HVEM axis holds immense potential for future development of cancer immunotherapy strategies." (PMID 37649037, 2023). "In this study, we demonstrated that BTLA is transcribed in various cancer cell lines and further confirmed the BTLA expression by RT-PCR, immunoblot, and flow cytometry." (PMID 36552785, 2022). "Next to widely studied ICs like PD-1 and CTLA-4 recently also B and T lymphocyte attenuator (BTLA) emerged as important IC in cancer." (PMID 36741370, 2022). "B- and T-lymphocyte attenuator (BTLA) is a receptors expressed on the surface of T cells, B cells, DC, and myeloid cells with significantly higher expression in cancer patients compared to healthy controls." (PMID 36612180, 2022). "Real-time quantitative reverse transcription polymerase chain reaction (qRT-PCR) and RT-PCR for these cancer cells demonstrated that BTLA messenger RNA (mRNA) was transcribed in all examined cancer cell lines." (PMID 36552785, 2022). "We also demonstrated that TMEM59L expression was negatively linked with the expression of many immune modulators, including PD-L1, IDO1, TIGIT, CTLA-4, and BTLA in various cancers." (PMID 36618425, 2022). "Together with the increasing number of reports promoting BTLA as a prognostic marker in cancer, mechanistic studies on how, and to what extent sBTLA modifies the immune response are motivated." (PMID 35312715, 2022). "PDCD1, CD274, CTLA4, LAG3, C10orf54, and BTLA expression had positive correlations in most cancer types, and in approximately half of the cancer types, GBP1 expression is positively correlated with CD276 expression." (PMID 35222540, 2022). "Cancers with elevated circulating levels of soluble form of BTLA include HCC, pancreatic adenocarcinoma, clear cell renal cell carcinoma and prostate cancer." (PMID 34531847, 2021). "These outcomes indicate a broader regulatory role for BTLA in cancer as compared to PD-1 and CTLA-4 checkpoint axis." (PMID 34531847, 2021). "Some recent studies have revealed a significant correlation between BTLA SNPs and development of cancer." (PMID 33564688, 2021). "Analyses of gene and protein expression based on inflammation and carcinogenesis suggested that the decreases in CCL21 and BTLA are important in cancer chemoprevention by Fx." (PMID 34948416, 2021). "Several cancers have shown up-regulation of BTLA and its blockade has displayed an enhanced immune response." (PMID 34531847, 2021).
cancer (continued). "BTLA was a member of the TNF superfamily, and its expression was associated with cancer aggressiveness." (PMID 34291083, 2021). "Other newer costimulatory and coinhibitory molecules belonging to CD28-B7 family receptors are being discovered and investigated for their role in cancer immune evasion such as BTLA, B7-H3, B7-H4, and B7-H5, etcetera." (PMID 34531847, 2021). "New inhibitory checkpoint proteins such as B7-H3, B7-H4, and BTLA (B and T lymphocyte attenuator) are being discovered and investigated for their potential in anti-cancer immunotherapy." (PMID 34531847, 2021). "Collectively, these studies point towards a correlation between BTLA and the development and progression of human cancers." (PMID 33564688, 2021). "The correlation between clinical characteristics and BTLA expression remains inconsistent depending on the cancer type." (PMID 34948416, 2021). "Other IRs have also been discussed as potential targets for cancer immunotherapy, including Tim3, BTLA, and TIGIT." (PMID 32451453, 2020). "Frequency of genetic variants of CTLA-4, PDCD1, PD-L1, BTLA, HAVCR2, and LAG3 genes (in different human populations) for which the association with cancer risk has been investigated." (PMID 33519815, 2020). "This review will summarize current knowledge about the impact of the genetic variants of CTLA-4, PDCD1, PD-L1, BTLA, TIM-3, and LAG-3 on cancer risk." (PMID 33519815, 2020). "A new anticancer therapy based on the blockade of the BTLA signaling pathway was proposed next, which signaled the beginning of a new chapter in cancer intervention." (PMID 30984188, 2019). "Recently, many investigations have focused on the relationship of BTLA with inflammation, autoimmune disease and cancer." (PMID 31774112, 2019). "Published studies also suggest that gene BTLA is relevant to the occurrence and development of many cancer types." (PMID 31405076, 2019). "Nevertheless, the role of BTLA in thyroxine-induced pro-inflammatory actions and cancer proliferation is not yet well understood." (PMID 31817534, 2019). "Preventing/targeting the BTLA/HVEM interaction can reverse the inhibitory functions of BTLA, thus triggering the immune response against cancer." (PMID 28594868, 2017). "Intriguingly, MFIs of BTLA or CTLA-4 on CD4+ T cells from cancer patients were significantly higher than that from normal donors." (PMID 27577071, 2016). "The over-expression of BTLA (as well as its ligand HVEM) was observed in cancers, especially in malignant T lymphoproliferative disorders." (PMID 27933341, 2016). "At day 5 post-infection, endogenous CD4+ T cells in the cancer group had an inhibitory receptor profile consistent with phenotypic exhaustion with increased expression of BTLA and 2B4." (PMID 24796533, 2014). "At day 5 post-infection, CD8+Thy1.1+ T cells isolated from the cancer group had statistically significant higher frequencies BTLA+ cells as compared to the control group." (PMID 24796533, 2014). "More recently, the “exhaustion marker” value of PD1 and BTLA has been alternatively reviewed in the context of both cancer and T cell differentiation." (PMID 24391639, 2013). "BTLA is overexpressed in various cancers, leading to an impaired antitumor response." (PMID 40574024, 2025). "Both trials cited here demonstrate that the choice of BTLA as a therapeutic target may contribute to current efforts to discover new classes of antibodies to combat certain forms of cancer." (PMID 41440959, 2025). "With continued scientific and translational progress, BTLA-targeted immunotherapy may soon become an important addition to the expanding arsenal of cancer treatment options." (PMID 41471273, 2025). "We then examine how BTLA expression levels affect patient prognosis across different cancer types and consider its emerging potential as a prognostic biomarker that may inform risk stratification and treatment decisions." (PMID 41471273, 2025). "In the context of cancer, BTLA’s regulation of B cells can have dual implications." (PMID 41471273, 2025).